SDHA (succinate dehydrogenase complex flavoprotein subunit A)
Diseases named in the same sentence as SDHA in open-access papers (continued):
Sharing a sentence is not in itself a finding about the gene and the disease.
gastrointestinal stromal tumor (29 papers, 2012 to 2026). "And the notable immunohistochemical loss of SDHA in gastrointestinal stromal tumors (GISTs) signals mutation of SDHA." (PMID 36949947, 2023). "Mutations in sdhA are also sometimes associated with cancers, notably gastrointestinal stromal tumors, about 7.5% of which involve complex II deficiency, mostly involving sdhA alleles." (PMID 35563430, 2022). "SDHA mutations have also been reported in gastrointestinal stromal (GIST) tumors." (PMID 37508015, 2023). "The fourth patient was diagnosed with a gastrointestinal stromal tumour (GIST) (PaedCan71), in whom we identified a variant in SDHA, a heterozygous duplication of exon 4-11, initially classified as VUS." (PMID 37507557, 2023). "SDHA mutation rate was higher in glioma and gastrointestinal stromal tumor (GIST) AYAs." (PMID 36433963, 2022). "Germline SDHA PVs are associated with an increased risk of paraganglioma (PGL), pheochromocytoma (PCC), gastrointestinal stromal tumor (GIST), and renal cell carcinoma." (PMID 38770192, 2024). "Germline mutation of the succinate dehydrogenase subunit genes, SDHA, SDHB, SDHC or SDHD, is associated with increased risk for paraganglioma (PGL), pheochromocytoma (Pheo), gastrointestinal stromal tumor (GIST) and renal cell carcinoma." (PMID 36455002, 2022). "In contrast with SdhA, mutations in the other subunits SdhB-D are generally associated with cancers, especially paragangliomas (PGL) and phaeochromocytomas (PCC), but also with other cancers including renal carcinoma, thyroid cancer, ovarian cancer, neuroblastoma and gastrointestinal stromal tumor." (PMID 35563430, 2022). "SDH-deficient gastrointestinal stromal tumors (GIST) account for 20–40% of all KIT/PDGFRA-negative GIST and are due to mutations in one of the four SDH-complex subunits, with SDHA mutations as the most frequent." (PMID 35059314, 2021). "It comprises four subunits (SDHA, SDHB, SDHC and SDHD), any of which may be targeted in a subset of gastrointestinal stromal tumors (GIST) leading to SDH deficiency." (PMID 33921435, 2021). "Heterozygous germline mutations in SDH complex (SDHx) genes (SDHA, SDHB, SDHC, SDHD, and SDHAF2), which act as tumor suppressor genes, predispose to pheochromocytomas and paragangliomas (PPGLs) and rarely to gastrointestinal stromal tumors (GIST), renal cell carcinoma, and pituitary adenomas." (PMID 35892689, 2022).
Leigh syndrome (25 papers, 2005 to 2026). "SDHA encoding a subunit of the Krebs cycle enzyme succinate dehydrogenase is among the nuclear genes associated with the Leigh syndrome spectrum that impact mitochondrial energy metabolism." (PMID 41546701, 2026). "In the most severe cases, SDHA deficiency in humans causes Leigh syndrome, a devastating disorder that arises from defects in oxidative phosphorylation or related processes which contribute to mitochondrial energy production." (PMID 36465130, 2022). "Most clinically affected individuals reported in the literature harbor pathogenic variants within the SDHA gene and present with a Leigh syndrome, epileptic encephalopathy, and cardiomyopathy." (PMID 35892689, 2022). "The first recessive SDHA gene mutation was reported in two siblings diagnosed in early childhood for a typical Leigh syndrome, hallmarked by the hypodensity of the white matter revealed by a computer tomography scan (CT scan)." (PMID 35892689, 2022). "SdhA mutations have been linked to the progressive neurodegenerative disorder Leigh syndrome and the promotion of Sdh activity can prevent neurodegeneration in Drosophila." (PMID 36008977, 2022). "In humans, SDH activity is positively correlated with sperm quality, and mutations in SDHA are associated with Leigh Syndrome." (PMID 36465130, 2022). "Homozygous or compound heterozygous SDHA variants have been found in patients with Leigh syndrome, leukodystrophy, cardiomyopathy, and progressive neuromuscular decline." (PMID 33960148, 2021). "Bi-allelic mutations of SDHA were described in Leigh syndrome, an early-onset, progressive neurodegenerative disease caused by defective mitochondrial bioenergetics." (PMID 33803845, 2021). "Complex II deficiency is rare accounting for only 2–4% of OXPHOS defects, with variants in SDHA being most common, predominantly associated with Leigh syndrome." (PMID 34012134, 2021). "Homozygous mutations of SDHA gene (5p15) cause a clinical phenotype (Leigh syndrome) characterized by degenerative myeloencephalopathy." (PMID 32326947, 2020). "The final pathogenic SDHA splicing variant, c.248C>T, was identified in a child who presented at 5 months of age with Leigh syndrome and seizures and was found to have hypsarrhythmia on EEG (Case 7)." (PMID 33162331, 2020). "In 1995, the first pathological variants in an ETC nuclear-encoded gene succinate dehydrogenase subunit A (SDHA) in Complex II was described in two sisters with Leigh syndrome." (PMID 33426505, 2020). "The vast majority of clinically-affected individuals reported in the literature harbour genetic variants within the SDHA gene and present with a Leigh syndrome phenotype, clinically defined as a subacute necrotising encephalopathy." (PMID 33162331, 2020). "Succinate dehydrogenase (SDHA) mutations not only can result in the severe neurological disorder Leigh Syndrome, but also in one extended family can cause dilated cardiomyopathy." (PMID 30478029, 2018). "Among the SDH genes, homozygous germline mutations in the SDHA gene are associated with Leigh syndrome, which most commonly arises at an early age and is characterized by central nervous system impairment." (PMID 28187001, 2017). "A total of nine germline variants (three missense, six truncating) in SDHA, associated with either optic atrophy or Leigh syndrome were identified in the literature." (PMID 28546994, 2017). "Unlike SDH-loss PGL (a disorder displaying autosomal dominant inheritance), Leigh syndrome displays recessive inheritance requiring inherited mutations in both SDHA alleles." (PMID 26294907, 2015).
Leigh syndrome (continued). "Germline mutations in SDHA are associated with neurodegenerative diseases such as an early-onset encephalopathy, known as Leigh syndrome and a late-onset optic atrophy, ataxia and myopathy." (PMID 22974104, 2012). "Pathogenic mutations in the SDHA gene have rarely been documented in children, and all but one case have been reported in patients with Leigh syndrome." (PMID 22830024, 2012). "Mutations in the SDHA gene were found to be associated with Leigh syndrome, late onset neurodegenerative disease and dilated cardiomyopathy." (PMID 22995659, 2012). "Biallelic variants in the SDHA subunit most often cause Leigh syndrome." (PMID 41635801, 2026). "SDHA mutations cause mitochondrial disease, such as Leigh syndrome (LS) and multisystem (ocular, cardiomyopathy and neurological) disorders, and result in a significant tissue-specific reduction in SDH enzymatic activity, which has been linked to significant clinical phenotypes." (PMID 38254943, 2023). "The second SDHA splicing variant was identified in a child who presented at 16 months of age with ataxia and myopathy and whose cranial MRI displayed changes consistent with Leigh syndrome (Case 12)." (PMID 33162331, 2020). "The second reported nonsense variant is a c.91C>T p.(Arg31*) SDHA substitution, identified in one patient who presented with Leigh syndrome and who died at 8 months of age (Case 8); the variant was identified in trans with a c.565T>G p.(Cys189Gly) SDHA variant." (PMID 33162331, 2020). "In addition, greatly increased rate of binding of the OAA to the enzyme in Leigh syndrome associated with a point mutation in SDHA was thought to account for the severity of the disease, supporting idea of OAA regulating complex II." (PMID 27287543, 2016). "The two main phenotypes associated with Complex II-encoded genes, SDHA, SDHB, SDHD, and the assembly factor SDHAF1 are associated with progressive encephalopathy leukodystrophy, Leigh syndrome, and/or cardiomyopathy." (PMID 33426505, 2020). "Inactivation of SDHA has been shown to promote neurodegenerative diseases like Leigh syndrome, which is an early-onset encephalopathy, as well as late-onset optic atrophy, ataxia, and myopathy." (PMID 31817761, 2019). "Mutations in SDHA, tafazzin, and FKTN were found to cause additional syndromes (Leigh syndrome (OMIM 256000), Barth (OMIM 30206), and muscular dystrophy dystroglycanopathy (OMIM 236670), resp)." (PMID 22830024, 2012). "The largest subunit, SDHA, is mutated in patients with Leigh syndrome and late-onset optic atrophy, but has not as yet been identified as a factor in hereditary cancer." (PMID 16288654, 2005).
breast carcinoma (19 papers, 2009 to 2025). "High expression of SDHA was associated with significantly reduced overall survival in breast cancer patients, whereas it was associated with increased survival in renal cancer patients." (PMID 40141095, 2025). "In conclusion, loss of SDHA or SDHB expression was detected in approximately 3% of the breast cancers in this study." (PMID 23888270, 2013). "Using similar methods in the present study, we found that 23 of 721 breast cancer patients (3.19%) had SDHA mutation (SDHA–/SDHB– expression) and one patient (0.1%) had an SDHB mutation (SHDA+/SDHB– expression)." (PMID 23888270, 2013). "In conclusion, loss of SDHA or SDHB expression was observed in about 3% of breast cancers in this study." (PMID 23888270, 2013). "Additionally, we found two cases with succinate dehydrogenase complex flavoprotein subunit A (SDHA) pathogenic variants; this gene is related to hereditary paraganglioma-pheochromocytoma syndrome, but has been found in two breast cancer cases." (PMID 36833268, 2023). "However, the loss of the SDH genes (SDHA or SDHB) is reported in only 3% of breast cancers." (PMID 36831625, 2023). "Furthermore, a previous study has reported loss of SDHA or SDHB expression in 3% of breast cancers." (PMID 32156290, 2020). "Nevertheless, in ovarian and breast cancer, SDHA subunit overexpression promotes an aggressive tumor phenotype characterized by an improved ability to survive, proliferate, and metastasize in anchorage-independent conditions." (PMID 40563592, 2025). "We observed an increased presence of succinate dehydrogenase complex subunit A (SDHA), a mitochondrial enzyme, in breast cancer (BC), which contributes to its proliferation." (PMID 40119440, 2025). "In other tumor types, the upregulation of the SDHA gene was driven by different mechanisms, including SDHA promoter hypomethylation in breast cancer or increased histone acetylation within the SDHA promoter in multiple myeloma." (PMID 40563592, 2025). "SDHA amplification has been described in ovarian and breast carcinomas, where it promotes metabolic reprogramming and sensitivity to agents such as shikonin." (PMID 41373665, 2025). "In a previous study investigating breast cancer, the protein expression level of SDHA and B was lost in 3% of the samples." (PMID 31164982, 2019). "In this study, more than 50% of breast cancers expressed SDHA and SDHB, which are key components of aerobic glucose metabolism through the TCA cycle and mitochondrial electron transport." (PMID 23888270, 2013). "Tumor negativity for SDHA correlated with earlier age at diagnosis of breast cancer (P = 0.012) and with lower histologic grade (P = 0.062)." (PMID 23888270, 2013). "An evaluation of those patients with incidental LPV/PV in SDHA (n = 21) showed that 10 (47.6%) were unaffected at the time of genetic testing, three (14.3%) had a personal history of prostate cancer, and two (9.5%) had a personal history of breast cancer." (PMID 39539798, 2024). "SDHA-negative breast cancers were associated with younger age at diagnosis (P = 0.012), and SDHB-negative breast cancers with lower histologic grade (P = 0.044) and lower Ki-67 labeling index (LI) (P = 0.046)." (PMID 23888270, 2013). "Immunohistochemical staining for ER, PR, HER-2, Ki-67, HIF-1α, SDHA, and SDHB was performed on tissue microarrays of 721 breast cancers." (PMID 23888270, 2013). "Patients with SDHA- and SDHB-negative breast cancers were also younger than patients with intact SDH expression, although in the case of SDHB, this difference was not statistically significant." (PMID 23888270, 2013). "Since HIF-1α is frequently expressed in breast carcinomas, DNA methylation at the promoter regions of the SDHA, SDHB, SDHC and SDHD and FH genes was evaluated as a possible mechanism in silencing of SDH and FH expression in breast carcinomas." (PMID 19778456, 2009). "The luminal A breast cancer subtype showed the highest frequency of low/negative SDHA expression (P = 0.032)." (PMID 23888270, 2013).
breast carcinoma (continued). "Similarly, the SDHA+/SDHB- and SDHA-/SDHB- breast cancers in this study were distinguished by lower histologic grade, and in the SDHB-negative tumors, by lower Ki-67 LI." (PMID 23888270, 2013). "No DNA methylation was identified in the promoter regions of the SDHA, SDHB, SDHC, SDHD and FH genes in 72 breast carcinomas and 10 breast cancer cell lines using methylation-sensitive high resolution melting which detects both homogeneous and heterogeneous methylation." (PMID 19778456, 2009). "Remarkably, Mdivi‐1 treatment increased the SDHa expression, again suggesting that mitochondrial fission driven by BET proteins might represent a valuable therapeutic target in breast cancer." (PMID 39223828, 2024). "HER-2 subtype breast cancers most frequently showed high-level expression of SDHA in tumor cells, while the luminal A subtype most frequently showed low or negative expression of SDHA in tumor cells (P = 0.032)." (PMID 23888270, 2013). "Clinicopathologic characteristics of breast cancers were compared between the SDHA/SDHB positive and negative breast cancers." (PMID 23888270, 2013). "In conclusion, promoter methylation of the SDHA, SDHB, SDHC, SDHD and FH genes is unlikely to be an important mechanism in stabilising HIF-1 in breast carcinomas through the downregulation of the expression of SDH and FH genes." (PMID 19778456, 2009). "However, stromal cells did not express SDHA and SDHB in most breast cancers in this study, which made it impossible to compare the staining intensity between tumor cells and internal normal controls (stromal cells)." (PMID 23888270, 2013).
metastatic disease (15 papers, 2012 to 2026). "In total, 18 patients suffered from metastatic disease; germline mutations in SDHA, SDHB and SDHC were present in one patient each, while SDHD mutations were found in seven patients." (PMID 35171114, 2022). "While one study using a Bayesian inference predicted a 1.7% penetrance of PPGL for patients with pathogenic variants in SDHA, the risk of metastatic disease in those with SDHA-related PPGL is up to 66%." (PMID 36010880, 2022). "Pathogenic variants in the succinate dehydrogenase subunit A gene (SDHA) have been shown to cause metastatic disease, occurring in various regions of the body." (PMID 36010880, 2022). "Although the penetrance is low, the rate of metastatic disease for those with SDHA-associated PCC/PGL is high at 12%." (PMID 37435466, 2022). "Although pathogenic variants of SDHA leading to CBTs are rare due to low penetrance, patients with SDHA-associated CBTs may have an increased risk of contracting metastatic disease." (PMID 38339335, 2024). "Meta-analyses have also been conducted in the other SDH variants, revealing the metastatic disease prevalence of 23% to 31% for SDHB, 23% for SDHC, 16% for SDHA, and 6% to 8% for SDHD." (PMID 41183483, 2026). "To date, the NGS study of the tumor is only performed in research clinics for malignant, already metastatic tumors; in routine surgeries, molecular characterization, when there is any, involves only immunohistochemical analysis for SDHA and SDHB proteins." (PMID 39457697, 2024). "While metastatic disease risk is estimated to be low for SDHC mutations, metastatic risk in SDHA is 30-66%." (PMID 35903274, 2022). "Compared with SDHA-related metastatic disease, the age at diagnosis among patients with SDHB-related metastatic disease was younger at 31 years old." (PMID 30854332, 2019). "In conclusion, SDHA-related metastatic PHEO/PGLs behave like SDHB-related metastatic disease, showing aggressive behavior, similar imaging and biochemical phenotypes, and suboptimal responses to conventional treatments." (PMID 30854332, 2019). "In our analyses of risk rate not adjusted for time, we found a significantly increased risk of metastatic disease in patients with pathogenic germline variants in SDHA, SDHB, SDHC, TMEM127, MAX, and FH compared to those with no identified pathogenic variant." (PMID 41183483, 2026). "SDHA pathogenic carriers can develop PCC/PGL at any location in the body, including head and neck PGLs and patients who develop SDHA mutation related PCC/PGL report to have high rates of metastatic disease (12%)." (PMID 36699028, 2022). "Two patients with SDHB mutations and one patient with SDHD mutation were characterized by metastatic tumors but no SDHA variants were detected." (PMID 33391357, 2020). "Unfortunately, there is a paucity of data regarding SDHA-related metastatic disease." (PMID 30854332, 2019). "Given the higher risk for metastatic disease in patients with SDHB PVs and reported cases of early-onset of disease during childhood, it is proposed to start screening at age 6–10 for asymptomatic SDHB PV carriers and at age 10–15 for carriers of PVs in SDHA, SDHC, and SDHD genes." (PMID 37435466, 2022). "Our analysis also shows sexual differences among patients with SDHA PVs in that males had more often PGL and metastatic disease than females." (PMID 38481600, 2024). "Three tumors were from patients who developed metastatic disease (E205, PC, EPAS1; E206, PC, EPAS1; E235, PC, MAML3-fusion), and two tumors had locally invasive features (E007, TMEM127; E025, AT-PG, SDHA)." (PMID 36271074, 2022). "Other investigations on SDHA-related PHEO/PGL report the proportion of metastatic disease to be ranging from 9 to 33% compared to 66.67% in our cohort of patients." (PMID 30854332, 2019). "In our cohort of SDHA patients, bone metastases were the most abundant lesions compared to all other types of metastases combined, which is consistent with findings in all PPGL-related metastatic disease." (PMID 36010880, 2022).
metastatic disease (continued). "These treatments show promise in SDHA-related metastatic PHEO/PGL and are worth studying to establish their efficacy and safety for this type of patients, especially those who present with inoperable tumors including metastatic disease." (PMID 30854332, 2019).
pituitary adenoma (14 papers, 2015 to 2025). "They identified SDHA mutations (c.1873C>T, p.His625Tyr) in a patient with a non-functional pituitary macroadenoma, marking the first report of an association between SDHA gene mutations and pituitary adenomas." (PMID 39765842, 2024). "All pituitary adenomas showed intact staining for both SDHA and SDHB." (PMID 32252027, 2020).